SNORD114-5 (small nucleolar RNA, C/D box 114-5)
Synonyms: 14q(II-5)
Gene: Small nucleolar RNA gene on chromosome 14 (100,955,370 to 100,955,439, forward strand). Ensembl gene ENSG00000199798.
Gene Ontology:
Biological process: RNA processing
Cellular component: nucleolus
Homologues: Orthologues: chimpanzee SNORD114-5 (100% identical), macaque SNORD114-5 (93% identical). Paralogues in human: SNORD114-23 (94% identical), SNORD114-28 (91% identical), SNORD114-15 (90% identical), SNORD114-25 (90% identical), SNORD114-26 (90% identical), SNORD114-20 (89% identical), SNORD114-21 (89% identical), SNORD114-9 (89% identical), SNORD114-13 (87% identical), SNORD114-22 (87% identical), SNORD114-3 (87% identical), SNORD114-29 (86% identical), and 26 more.